RNU6-530P (RNA, U6 small nuclear 530, pseudogene)
Gene: Small nuclear RNA gene on chromosome 7 (79,343,266 to 79,343,372, reverse strand). Ensembl gene ENSG00000212482.
Homologues: Orthologues: chimpanzee U6 (100% identical), macaque U6 (94% identical), rabbit U6 (75% identical), pig U6 (73% identical), guinea pig U6 (67% identical). Paralogues in human: RNU6-1060P (85% identical), RNU6-1147P (85% identical), RNU6-19P (85% identical), RNU6-317P (84% identical), RNU6-1020P (83% identical), RNU6-1152P (83% identical), RNU6-116P (83% identical), RNU6-15P (83% identical), RNU6-24P (83% identical), RNU6-266P (83% identical), RNU6-43P (83% identical), RNU6-657P (83% identical), and 1286 more.